TMEM132A (transmembrane protein 132A)
Description:
May play a role in embryonic and postnatal development of the brain. Increased resistance to cell death induced by serum starvation in cultured cells. Regulates cAMP-induced GFAP gene expression via STAT3 phosphorylation (By similarity).
Synonyms: HSPA5BP1; GBP; FLJ20539
Tractability: Antibody: UniProt predicts a signal peptide or a membrane-spanning region; its Gene Ontology location is reachable by antibodies, with medium confidence. PROTAC: ubiquitination databases record sites on it; its protein half-life has been measured.
Gene: Protein-coding gene on chromosome 11 (60,924,460 to 60,937,159, forward strand). Ensembl gene ENSG00000006118.
Subcellular location: Golgi apparatus membrane; Endoplasmic reticulum membrane
Subcellular location (Human Protein Atlas): Mitochondria
Pathways (Reactome):
Metabolism of proteins: Post-translational protein phosphorylation; Regulation of Insulin-like Growth Factor (IGF) transport and uptake by Insulin-like Growth Factor Binding Proteins (IGFBPs)
Gene Ontology:
Molecular function: protein homodimerization activity
Biological process: positive regulation of Wnt signaling pathway
Cellular component: extracellular exosome; endoplasmic reticulum lumen; membrane; endoplasmic reticulum; endoplasmic reticulum membrane; Golgi membrane; plasma membrane
Genetic constraint (gnomAD): Loss-of-function variants: 49 observed, 60.59 expected, observed/expected ratio (o/e) 0.81, 90% interval 0.64 to 1.03. The upper end of that interval is the gene's LOEUF score, 1.03, which puts it in group 4 of 6, group 1 being the genes least tolerant of losing a copy. Missense variants: 1,276 observed, 1,321.3 expected, observed/expected ratio (o/e) 0.97, 90% interval 0.92 to 1.01. Synonymous variants: 572 observed, 573.76 expected, observed/expected ratio (o/e) 1, 90% interval 0.93 to 1.07.
Homologues: Orthologues: chimpanzee TMEM132A (99% identical), macaque TMEM132A (97% identical), rabbit TMEM132A (89% identical), rat Tmem132a (87% identical), mouse Tmem132a (87% identical), dog TMEM132A (86% identical), pig TMEM132A (85% identical), guinea pig TMEM132A (77% identical), zebrafish si:dkey-1d7.3 (25% identical), Drosophila melanogaster dtn (24% identical), Caenorhabditis elegans tmem-132 (16% identical). Paralogues in human: TMEM132C (34% identical), TMEM132D (33% identical), TMEM132E (33% identical), TMEM132B (32% identical).
Diseases named in the same sentence as TMEM132A in open-access papers:
TMEM132A is named in the same sentence as 17 diseases in open-access papers, as found by Europe PMC text mining. Sharing a sentence is not in itself a finding about the gene and the disease. The quoted sentences say what the papers report.
gastric cancer (2 papers, 2024). A primary or metastatic malignant neoplasm involving the stomach. "We found that TMEM132A plays an oncogenic role in regulating cell proliferation, migration, and invasion in gastric cancer." (PMID 38974022, 2024).
glioblastoma (1 paper, 2022). The most malignant astrocytic tumor (WHO grade IV). "In addition, TMEM132A is also reported to regulate the expression of cAMP-induced glial fibrillary acidic protein in rat C6 glioblastoma cells." (PMID 35501731, 2022).
hemangioma (1 paper, 2022). A benign vascular lesion characterized by the formation of capillary-sized or cavernous vascular channels. "Of note, we found that TMEM132A is related to TGF-β signaling and Notch signaling pathway in hemangioma by GSEA analysis, which is conducive to further research." (PMID 35501731, 2022). "Finally, three genes (APLN, APLNR, TMEM132A) were identified as hub genes, which were consistently highly expressed in hemangioma tissues, regardless of different stages, through integrated WGCNA and PPI network analysis of DEGs." (PMID 35501731, 2022). "However, there is no related research report of TMEM132A in hemangioma." (PMID 35501731, 2022).
metabolic syndrome (1 paper, 2023). A cluster of metabolic risk factors for CARDIOVASCULAR DISEASES and TYPE 2 DIABETES MELLITUS. "Seven metabolic syndrome-related genes (CSF3R, TMEM132A, STAB1, VIM, DUOXA1, PILRB, and SLC2A4) were used to construct risk equations." (PMID 37033267, 2023).
multiple myeloma (1 paper, 2025). "While there is a paucity of research investigating the effects of metformin on TMEM132A, a recent study reported that metformin treatment suppresses GRP78 to enhance apoptosis in multiple myeloma, suggesting this may be a mechanism by which metformin exerts its antineoplastic effects." (PMID 40136342, 2025).
prostate carcinoma (1 paper, 2022). A carcinoma that arises from epithelial cells of the prostate gland. "TMEM132A (transmembrane protein 132A) is regarded as a novel regulator of Wnt signaling pathway, which drives prostate cancer bone metastatic tropism and invasion." (PMID 36195908, 2022). "As results, high KCTD4 expression, low THBS2 expression, and high ACPP expression were associated with favorable BCRFS of prostate cancer patients; and high expression levels of HOPX, TMEM132A, and ZNF467 were associated with shorter MFS of prostate cancer patients." (PMID 36195908, 2022).
spina bifida (1 paper, 2020). A congenital neural tube defect in which vertebrae are not fully formed. "In on-going studies of neural tube defects, we became interested in TMEM132A, loss of which causes spina bifida in mice." (PMID 33324648, 2020).
tumor (7 papers, 2016 to 2025). "Furthermore, TMEM132A was significantly associated with immune checkpoints, immunomodulators, prognosis, immunomodulatory genes, tumor stemness score, cell function status and immune infiltration in most tumors." (PMID 38947398, 2024). "We analyzed TMEM132A expression and its correlation with clinical survival, immune checkpoints, tumor stemness score, prognostic value, immunomodulators, genomic profiles, immunological characteristics, immunotherapy and functional enrichment." (PMID 38947398, 2024). "As for TMEM132A, few studies were found in the literature, so further investigations are required to establish its role in tumor development." (PMID 35954418, 2022). "Cox regression analyses were performed to identify independent clinical prognostic parameters to construct a combined nomogram which includes the expression of CERCAM, MIA2, HS6ST2, ONECUT2, SOX12, TMEM132A, pT stage, tumor size and ISUP grade." (PMID 35954418, 2022). "Also, high expression of TMEM132A can activate the Wnt/β-catenin signaling pathway, and the regulatory role of the Wnt/β-catenin signaling pathway in various diseases, including the tumor microenvironment, has been proven." (PMID 40432920, 2025). "Consistent with the bioinformatic prediction, GTF3C1, NR1H3, NTHL1, SNX, TMEM132A and WIZ expressions were markedly upregulated in the tumor group relative to the normal group." (PMID 41573564, 2025). "Through RNA-Seq analysis of HNSCC samples (3 tumors and 3 para-carcinoma tissues), we identified 8 pivotal marker genes (PCDH7, CDH2, ITGA3, SEMA7A, TMEM132A, CD276, TMEM2, GPR158) that were overexpressed in tumor specimens." (PMID 38548747, 2024). "More than half of the genes were not DE in any tumor type, while seven genes (C7, ADH1B, HSPB6, FXYD1, PLAC9, TMEM132A and ASF1B) were DE in all tumor types." (PMID 26655252, 2016). "In addition, all urinary proteins, except for four (TMEM132A, HLA-DRB1, SLC10A3, RNF150), have been reported as candidate biomarkers for thirty-five neoplastic diseases." (PMID 36918772, 2023).
cancer (5 papers, 2021 to 2025). A tumor composed of atypical neoplastic, often pleomorphic cells that invade other tissues. "TMEM132A is a multifunctional transmembrane protein which plays a key role in many physiological and pathological processes such as cell adhesion, signal transduction, cancer development and neurodevelopment." (PMID 40432920, 2025). "This may help us to better understand how TMEM132A plays a role in cancer and provide valuable insights for developing personalised treatments." (PMID 38947398, 2024). "However, while some studies have investigated the involvement of TMEM132A in specific cancers, further systematic studies are required to elucidate its specific mechanisms of action in different cancer types." (PMID 38947398, 2024). "In addition, high TMEM132A expression may have a higher prognostic value in some cancers." (PMID 38947398, 2024). "High expression of CERCAM, HS6ST2, ONECUT2, SOX12 and TMEM132A and low expression of MIA2 related to poor outcomes for progression-free survival and cancer-specific survival." (PMID 35954418, 2022). "In addition to the reported genes related to cancer cell stemness, our results also showed many genes that had not been reported to be related to cancer cell stemness, especially to PCa cell stemness, such as TEDC2, TMEM132A, and VARS, etc." (PMID 33985534, 2021).
TMEM132A also shares sentences with these, for which no sentence is quoted: bladder cancer (1 paper); lung adenocarcinoma (1); metabolic disease (1); Obesity (1); ovarian carcinoma (1); sarcoma (1); urological disease (1); venous thromboembolism (1).